PLEKHO2 (pleckstrin homology domain containing O2)
Synonyms: PLEKHQ1; PP9099; DKFZp761K2312; PP1628
Tractability: Antibody: its Gene Ontology location is reachable by antibodies, with high confidence; the Human Protein Atlas places it where antibodies can reach. PROTAC: ubiquitination databases record sites on it; its protein half-life has been measured.
Gene: Protein-coding gene on chromosome 15 (64,839,231 to 64,868,002, forward strand). Ensembl gene ENSG00000241839.
Subcellular location (Human Protein Atlas): Cytosol; Plasma membrane; Nucleoplasm
Pathways (Reactome):
Immune System: Neutrophil degranulation
Gene Ontology:
Biological process: macrophage apoptotic process
Cellular component: extracellular region; ficolin-1-rich granule lumen
Genetic constraint (gnomAD): Loss-of-function variants: 21 observed, 33.32 expected, observed/expected ratio (o/e) 0.63, 90% interval 0.45 to 0.91. The upper end of that interval is the gene's LOEUF score, 0.91, which puts it in group 3 of 6, group 1 being the genes least tolerant of losing a copy. Missense variants: 568 observed, 643.82 expected, observed/expected ratio (o/e) 0.88, 90% interval 0.82 to 0.95. Synonymous variants: 247 observed, 254.09 expected, observed/expected ratio (o/e) 0.97, 90% interval 0.88 to 1.08.
Homologues: Orthologues: chimpanzee PLEKHO2 (100% identical), pig PLEKHO2 (86% identical), dog PLEKHO2 (82% identical), rabbit PLEKHO2 (78% identical), mouse Plekho2 (78% identical), rat Plekho2 (75% identical), guinea pig PLEKHO2 (71% identical), tropical clawed frog plekho2 (38% identical), zebrafish plekho2 (37% identical). Paralogues in human: PLEKHO1 (24% identical).
Diseases named in the same sentence as PLEKHO2 in open-access papers:
PLEKHO2 is named in the same sentence as 6 diseases in open-access papers, as found by Europe PMC text mining. Sharing a sentence is not in itself a finding about the gene and the disease. The quoted sentences say what the papers report.
Hepatitis (1 paper, 2021). Inflammation of the liver. "Ultimately, PLEKHO2-deficient mice display greatly increased hepatotoxicity and lethality after TNFα-induced hepatitis." (PMID 34272357, 2021). "Moreover, PLEKHO2-deficient mice display greatly increased hepatotoxicity and ultimately lethality after TNFα-induced hepatitis." (PMID 34272357, 2021).
lung squamous cell carcinoma (1 paper, 2021). "A previous study reported that PLEKHO2 was significantly down-regulated in lung squamous cell carcinoma compared with normal tissues." (PMID 34070923, 2021).
osteosarcoma (1 paper, 2023). A usually aggressive malignant bone-forming mesenchymal neoplasm, predominantly affecting adolescents and young adults. "Four gene expression signatures (PLEKHO2, GBP2, MPP1, and VSIG4) linked to osteosarcoma prognosis were identified within the TARGET-osteosarcoma cohort, categorizing patients into two subgroups." (PMID 38169731, 2023). "Although PLEKHO2, VSIG4, MPP1, and GBP2 have been implicated in the pathogenesis of several cancers, their roles in osteosarcoma have not been reported to date." (PMID 38169731, 2023). "Finally, we focused on investigating the role of GBP2 in osteosarcoma and did not extensively explore the functions of PLEKHO2, VSIG4, and MPP1." (PMID 38169731, 2023).
PLEKHO2 also shares sentences with these, for which no sentence is quoted: tumor (2 papers); cancer (1); colorectal cancer (1).